SYK (spleen associated tyrosine kinase)
Diseases named in the same sentence as SYK in open-access papers (continued):
Sharing a sentence is not in itself a finding about the gene and the disease.
lymphoma (continued). "Owing to the multiple roles of SYK in the cell, the dysfunction of SYK signaling has been reported in various diseases and disorders such as allergic rhinitis, asthma, autoimmune disease rheumatoid arthritis, psoriasis, systematic lupus erythematosus, leukemia, and lymphomas." (PMID 35846777, 2022). "In our study, the prognosis of the SYK high‐risk group is better than that of the low‐risk group, which may be attributed to the absent expression of SYK in some lymphoma with worse prognosis." (PMID 33259129, 2021). "Besides antigen-dependent BCR stimulation, SYK activity has also been shown to be regulated by mutated MYD88L256P that forms the myddosome signaling complex and activates STAT3 and Akt signaling in MYD88L256P lymphoma cells." (PMID 32455989, 2020). "Indeed, SYK has been a target of interest in B cell acute lymphoblastic leukemia and lymphomas." (PMID 29719615, 2018). "Primary data from this phase I, first-in-human study investigating the safety, tolerability, and preliminary efficacy of SYK/FLT3 inhibitor mivavotinib, conducted in patients with advanced solid tumors or lymphoma malignancies, were previously reported." (PMID 36702329, 2023). "For GC-DLBCL that shows a great dependency on AKT mediated by SYK activation, HSP90 targeting seems a good option to neutralize two client proteins essential for lymphoma survival." (PMID 36765939, 2023). "The ability of LUX to reduce steady-state and anti-IgM-induced phosphorylation of SYK was more than 100-fold greater for LUX than for IB and was observed in all the three lymphoma cell lines studied." (PMID 36888611, 2023). "Of note, the pattern of LCK expression is similar to oncogenes SYK and BTK, which are known drivers of B-cell leukemia and lymphoma." (PMID 36711753, 2023). "Various small molecules engaging BCR or its downstream signaling, such as BTK, CDK, PI3K, BCL-2 or SYK inhibitors, have shown synergistic activity with BET inhibition in lymphomas." (PMID 36230614, 2022). "SYK is currently addressed in different clinical trials e.g. by the inhibitor Entospletinib for CLL, AML, ALL, and Lymphoma." (PMID 32817744, 2020). "The role of SYK in B-cell receptor (BCR) initiated tonic signaling both in normal B-cells and lymphomas is well established." (PMID 24564859, 2013). "We found increased basal levels of several phospho-proteins in lymphoma B cells, whereas they overall had impaired, but sustained anti-BCR-induced p-PLCγ, p-SYK/Zap70, p-SFKs and p-ERK, compared to healthy donor B cells." (PMID 23072591, 2012). "Inhibition of SYK with a small molecule drug candidate prevented oxidative stress-induced activation of STAT3 and overcame the resistance of human B-lineage leukemia/lymphoma cells to apoptosis." (PMID 23021489, 2012). "Collectively, these findings indicate that CEACAM1 not only plays an activating role but can also act as a negative regulator of BCR signaling in lymphoma cells with low or absent CEACAM1 expression by preferentially binding to SHP-1 instead of SYK." (PMID 40436855, 2025). "In summary, in human lymphoma cells LUX and IB have quite distinct mechanistic effects on the phosphorylation of BTK and its activity, and on the upstream kinases SYK and LYN, and the adaptor protein BLNK against which LUX is very potent and IB had little effect." (PMID 36888611, 2023). "In addition to chronic BCR-activated leukemia and lymphoma, HSP90 also cooperates with BCR signaling in Burkitt lymphoma (BL) as it interacts with SYK in a BCR Y197-dependent manner." (PMID 36765939, 2023). "In lymphoma cells we found that LUX was a very potent at reducing the phosphorylation of SYK at Y525/Y526 whereas IB was not." (PMID 36888611, 2023). "We evaluated the anti-lymphoma activity of the isoform-specific bivalent BET inhibitor AZD5153 (AZD) and the pan-BET inhibitor I-BET151 (I-BET) as single agents and in combination with SYK inhibitor Entospletinib (Ento) in vitro." (PMID 36230614, 2022).
lymphoma (continued). "Knockdown of MYD88 or use of a MYD88 signaling inhibitor abrogated SYK activation, while expression of mutated but not wild-type MYD88 amplified p-SYK in MYD88-mutated and wild-type lymphoma cells." (PMID 32005797, 2020). "SYK and PI3K are both targets of clinically-approved inhibitors that are currently used in clinical trials against autoimmune thrombocytopenia (ITP), leukemia and lymphomas." (PMID 30930895, 2019). "Using a Myc-based lymphoma model, we had previously shown that LMP2A accelerates Myc-induced lymphomagenesis and that targeting LMP2A-modulated cellular kinases in this model was efficacious, encouraging our current studies exploring a new SYK inhibitor." (PMID 30135222, 2018). "SYK is a master regulator of apoptosis controlling the activation of the PI3-K/AKT, NFκB, and STAT3 pathways, three major anti-apoptotic signaling pathways in B-lineage leukemia/lymphoma cells." (PMID 24851191, 2014). "Whether the lymphoma patients whose lymphoma B cells’ have high basal levels of signaling proteins such as p-SFK and p-SYK, also are the ones with the greatest clinical responses upon specific kinase inhibitor therapy, should be the focus of future studies." (PMID 23072591, 2012). "Interestingly, the disease was treatable with SYK inhibitors (though a search of current Clinical Trials at the time of writing this review produced no current trials using SYK inhibitors against lymphoma)." (PMID 27725924, 2016). "A recently developed SYK inhibitor, TAK-659 (61, –, 64), is in clinical trials (NCT02000934, NCT02323113, NCT02834247, and NCT02954406), and preliminary clinical data indicate that it is nontoxic and highly effective against a subset of lymphomas (63, –, 66)." (PMID 30135222, 2018).
leukemia (38 papers, 2013 to 2025). A malignant (clonal) hematologic disorder, involving hematopoietic stem cells and characterized by the presence of primitive or atypical myeloid or lymphoid cells in the bone marrow and the blood. "Inhibition of SYK caused apoptotic death in primary leukemia cells from B-ALL patients that are resistant to chemotherapy." (PMID 36627892, 2022). "Our aim was to investigate and compare the effects of SYK inhibition on leukemia cells and to evaluate any associations with AML patient characteristics, e.g., mutational status or cytogenetics." (PMID 36499034, 2022). "Previous studies have identified a pathogenic role of SYK for the development of renal interstitial fibrosis, RA, leukemia, and liver fibrosis, suggesting a potential therapeutic intervention point for the treatment of such diseases." (PMID 31780731, 2019). "Most importantly, SYK inhibition causes apoptosis in primary leukemia cells from BPL patients that are resistant to chemotherapy." (PMID 24851191, 2014). "The SYK gene has been previously linked to leukemia progression." (PMID 38461240, 2024). "UBASH3B also positively regulates the SYK gene expression and its inhibition suppresses leukemia progression." (PMID 38461240, 2024). "In the present study, we explored the in vitro effects of five different SYK inhibitors on the viability and proliferation of primary leukemia cells derived from a large group of consecutive AML patients." (PMID 36499034, 2022). "The same groups reported that these compounds can also induce degradation of SYK and reduce SYK-driven leukemia cell proliferation." (PMID 34359655, 2021). "We found that targeted inhibition by small molecule inhibitors of USP10 impairs activated SYK-driven leukaemia cell proliferation and induces SYK protein degradation." (PMID 32015510, 2020). "Herein, we addressed the consequences of SYK inhibition to leukemia stem-cell (LSC) function and assessed SYK-associated pathways in AML cell biology." (PMID 33159047, 2020). "Activation of SYK by such alternative receptors contributes to maintenance of leukemia stem cells." (PMID 39665627, 2025). "UBASH3B also activates the oncogene SYK to promote leukemia growth." (PMID 38461240, 2024). "SYK also plays a key role in AML in terms of phosphorylating signal transducer and activator of transcription 5 (STAT5) and cooperating with FLT3-ITD in maintaining leukemia, and is also associated with an unfavorable prognosis." (PMID 35216478, 2022). "Interestingly, small-molecule inhibitors of USP10 have been found to inhibit the activated SYK-driven proliferation of leukemia cells and induce the degradation of SYK protein." (PMID 36248971, 2022). "Furthermore, our studies show that SYK suppression potentiates the anti‐leukaemic activity of FLT3 inhibition in cell line‐based models of mutant CBL‐positive leukaemia." (PMID 31943762, 2020). "Notably, SYK inhibition resulted in the ability to synergize with conventional ALL drugs to induce leukemia cells’ deaths at relapse." (PMID 31817853, 2019). "More interestingly, in patients that relapsed, the addition of entospletinib to VDA significantly increased the percentage of dead cells compared to VDA (p = 0.05) or to entospletinib (p = 0.0003) alone, highlighting the ability of SYK inhibition to sensitize leukemia cells to conventional drugs." (PMID 31817853, 2019). "Inhibition of SYK has shown promising results in Hodgkin lymphoma and leukemia." (PMID 29719615, 2018). "Importantly, our results also suggest that the effects of midostaurin can be potentiated by dual FLT3/SYK suppression or more targeted SYK suppression in the context of midostaurin-resistant leukemia and in FLT3-ITD-expressing primary cells." (PMID 28881711, 2017). "Interestingly, additional SYK suppression potentiated the effects of dual FLT3/SYK inhibitors and targeted FLT3 inhibitors against FLT3-ITD-driven leukemia, both in the absence and presence of activated SYK." (PMID 28881711, 2017).
leukemia (continued). "Oncogenic SYK has been identified as an important driver of different hematologic malignancies, including B-cell lymphoma, chronic lymphocytic leukemia (CLL) and mantle cell lymphoma, and was identified as a target in AML with SYK inhibition exhibiting anti-leukemia activity in mouse models of AML." (PMID 28881711, 2017). "Indeed, SYK inhibition prolonged survival of mice with Hoxa9/Meis1-driven leukemia." (PMID 35216478, 2022). "To test whether the accelerated leukemia development exhibited by H/S cells is dependent on SYK activation, we transplanted H cells expressing either hSYK or a hSYK Y348F/Y352F double mutant into lethally irradiated recipient mice and monitored overall survival." (PMID 28399410, 2017). "Spleen tyrosine kinase (SYK), stabilized by USP10, is critical for AML transformation and maintenance of the leukemia clone in AML patients." (PMID 34454635, 2021). "Here, we show that targeted SYK inhibition similarly enhances the effects of midostaurin and other FLT3 inhibitors against mutant CBL‐positive leukaemia." (PMID 31943762, 2020). "This pathway has been targeted in B-cell lymphomas and leukemias with several BCR-directed agents, such as inhibitors of Bruton's tyrosine kinase (BTK9), spleen tyrosine kinase (SYK) and phosphatidylinositol-3-kinase (PI3K)." (PMID 32211398, 2020). "According to the literature, spleen tyrosine kinase (SYK), phosphoinositide 3’kinase (PI3K), and Bruton’s tyrosine kinase (BTK) were selected because they have been related to decrease of leukemia cells in preclinical models." (PMID 31861689, 2019). "In order to assess SYK expression and activity in ETV6-RUNX1 leukemias, as a first step we evaluated three ETV6-RUNX1 cell lines (AT-1, AT-2 and REH) and two non-ETV6-RUNX1 ones (NALM-6 and RCH-ACV)." (PMID 31817853, 2019). "We show that midostaurin, like the dual FLT3/SYK inhibitors, R406 (tamatinib), and R788 (fostamatinib), inhibits SYK in cell-based models of FLT3-ITD- and activated SYK-driven leukemia to a greater extent than highly targeted inhibitors of FLT3." (PMID 28881711, 2017). "Small-molecule inhibitors of SYK induce AML differentiation and impair leukemia progression in preclinical studies." (PMID 26315286, 2015). "The over-expression schizophrenia genes involving the SYK and LCK genes play a key role in functional modularity in T cell, leukemia and lymphocyte activation which is crucial in immune-related responses." (PMID 24564241, 2013). "Additionally, SYK has been shown to be frequently activated in primary human DLBCL42, and is a target for several human leukemia therapies." (PMID 29674676, 2018). "Up to now, the activity of the multi-targeted FLT3 inhibitor, midostaurin, against cells expressing activated SYK has not been explored in the context of leukemia, although SYK has been identified as a target of midostaurin in systemic mastocytosis." (PMID 28881711, 2017). "Up to now, however, the activity of midostaurin, alone and combined with SYK inhibition, against cells expressing activated SYK has not been explored in the context of leukemia." (PMID 28881711, 2017). "As highly activated SYK has been found to occur at a higher frequency in AML patients harboring the ITD mutant than patients expressing wt FLT3, we were interested in exploring the activity of midostaurin against SYK using cell-based models of SYK-driven and SYK- and FLT3-driven leukemia." (PMID 28881711, 2017). "At least one of the SYK probesets was positively correlated with 33 out of the 38 probesets suggesting a high degree of co-regulation of SYK, SYK dependent STAT3 targets and anti-apoptotic genes in leukemia samples." (PMID 26285772, 2015). "However, additional targeted SYK inhibition or dual FLT3/SYK inhibition potentiates the effects of midostaurin and other inhibitors of FLT3 against both kinase inhibitor-sensitive- and -resistant FLT3-ITD- and activated SYK-positive leukemia." (PMID 28881711, 2017).
breast carcinoma (37 papers, 2004 to 2025). "Four breast cancer databases were assessed for focal deletion using single nucleotide polymorphism (SNP) Chip Profile in both SYK and PTEN genes." (PMID 32292575, 2020). "It has been further reported that loss of SYK expression through promoter hyper-methylation is associated with increased invasiveness of breast cancer cells." (PMID 32292575, 2020). "A study in human breast cancer also revealed reduced expression of SYK gene to be associated with poor prognosis." (PMID 31531378, 2019). "Transfection of breast cancer cells with a wild-type SYK encoding vector suppressed invasive outgrowth in Matrigel and impaired tumor growth and metastasis in mice." (PMID 30744170, 2019). "It is of note that SYK is expressed in normal luminal breast epithelial cells and in breast cancer cells its expression is associated to the luminal subtype and reduced invasiveness and metastasis." (PMID 28588211, 2017). "Strikingly, the results of our preliminary study of clinical breast cancer tissues revealed that SYK gene loss occurred in 5 out 19 samples of DCIS examined, but in none of 5 normal breast tissues examined." (PMID 24523870, 2014). "SYK loss in IDC was determined in a large breast cancer data set from The Cancer Genome Atlas (TCGA) using cBioPortal tools." (PMID 24523870, 2014). "SYK is located on human chromosome 9q22.2 and interestingly, allelic loss on chromosome 9q22 is associated with lymph node metastasis in primary breast cancer." (PMID 24523870, 2014). "Recently, several studies have identified SNPs and somatic mutations of SYK associated with breast cancer." (PMID 24523870, 2014). "SYK loss has been attributed to hypermethylation of the promoter in breast cancer tissues and its loss is associated with increased cellular invasiveness." (PMID 24523870, 2014). "Thus, our network analysis allowed identifying SYK targets that were specifically linked to breast cancer or Burkitt lymphoma specific subnetworks." (PMID 33670716, 2021). "Allelic deletion of SYK has been reported to be associated with higher incidences of breast cancer." (PMID 32292575, 2020). "Through a chemical genetic screen and a suite of drug mechanism-of-action studies, we here identify SYK-dependent STAT3 activation as a novel critical vulnerability of basal-like breast cancer cells, next to AURKA, which was previously implicated to be a potential target in BLBC." (PMID 25699542, 2015). "By employing chemical proteomics, structure–activity relationship studies and computational modeling, next to the previously implicated BLBC target AURKA, we identified the kinase SYK as being critically required for the viability of a subset of breast cancer cells." (PMID 25699542, 2015). "SYK copy number loss was found in about 26% of 1002 total breast cancer cases and 30% of IDC cases." (PMID 24523870, 2014). "To determine whether allelic loss of SYK might be associated with breast cancer invasion and progression in patient samples, we performed fluorescent in situ hybridization (FISH) to detect SYK alleles in a dual color FISH protocol." (PMID 24523870, 2014). "Previously, in patient samples, we demonstrated a loss of SYK mRNA in normal tissue adjacent to breast cancer, and further decreases in ductal carcinoma in situ (DCIS) and intraductal carcinoma (IDC) compared with normal or benign tissues where no cancer was detected." (PMID 24523870, 2014). "DNA methylation and loss of SYK expression has been reported in breast cancer." (PMID 14970867, 2004). "Fostamatinib is an oral spleen tyrosine kinase (SYK) inhibitor reported to suppress breast carcinoma metastasis by targeting the SYK-driven EMT process." (PMID 41373733, 2025). "SYK was reported to act as a tumour suppressor that inhibits tumorigenesis in breast cancer, while aberrant expression of SYK was found to be upregulated in PCa and related to aggressive progression." (PMID 38842134, 2024).